HMGB1 (high mobility group box 1)
Diseases named in the same sentence as HMGB1 in open-access papers (continued):
Sharing a sentence is not in itself a finding about the gene and the disease.
Stroke (continued). "Therefore, the disulfide bond HMGB1 isoform is a biomarker of inflammation, which indicates that blocking the extracellular disulfide bond HMGB1 isoform may be a potential direction for the treatment of inflammation and immune-related diseases, including stroke." (PMID 34372857, 2021). "Therefore, a clear grasp of HMGB1, NETs, and their roles in thrombosis in cerebral ischemia is important to devise strategies not only for ameliorating delayed inflammation and impaired recovery processes, but also for preventing secondary thrombi formation or even recurrent stroke." (PMID 32731558, 2020). "This is consistent with current evidence demonstrating HMGB1 mediated microglial activation via the HMGB1/TLR4/NFkB axis in several disease contexts, including Parkinson’s disease, stroke, and epilepsy." (PMID 33096930, 2020). "This study demonstrates that L-4F, an economical ApoA-I mimetic peptide, reduces neurovascular and WM damage via reducing proinflmammatory factors RAGE/HMGB-1 and TNFα/PAI-1 in the ischemic brain in db/db T2DM stroke mice." (PMID 31708728, 2019). "Our aim was to investigate the role of HMGB1 in the initiation and aggravation of PSI in a rat stroke model." (PMID 29555931, 2018). "Although numerous reports have shown the impact of PSI on the functional outcomes of stroke patients, this is the first report presenting a DAMP molecule, HMGB1, as a possible endogenous mediator." (PMID 29555931, 2018). "Anti-HMGB1 monoclonal antibody reduces infarct volume by 90% and potently reduces BBB permeability in stroke animal models." (PMID 30139371, 2018). "Therefore, HMGB1 might be a valuable therapeutic target for preventing post-stroke infection." (PMID 29555931, 2018). "A recent clinical study reported that the serum levels of HMGB1 were dramatically increased in patients with acute ICH, and this increase was significantly correlated with stroke severity." (PMID 28393932, 2017). "Furthermore, the blockade of HMGB1 release using an anti-HMGB1 monoclonal antibody, competitive antagonist, or short hairpin RNA has already been shown to be effective in various animal models of disease including traumatic brain injury, stroke, rheumatoid arthritis, acute pancreatitis, and cancer." (PMID 25114379, 2014). "Therefore, the HMGB1/RAGE axis may provide a target for therapy in stroke." (PMID 24065095, 2013). "Our results showed that the serum level of HMGB1 increased significantly after acute ICH and was significantly positively correlated with stroke severity." (PMID 20936104, 2010). "The serum level of HMGB1 increases dramatically in patients with acute ICH and is significantly positively correlated with the severity of the stroke." (PMID 20936104, 2010). "HMGB1, an essential ligand for RAGE, may be involved in stroke progression through the actions of neutrophils and macrophages." (PMID 38740617, 2025). "HMGB1 is a typical DAMP molecule that, in addition to being involved in neuroinflammation, has been found to mediate thrombosis, atherosclerosis, disruption of the blood–brain barrier, and, at a later stage, neurovascular remodeling and stroke recovery." (PMID 38740617, 2025). "Cytokine expression in both stroke types follows a biphasic pattern: an early pro-inflammatory phase dominated by TNF-α, IL-6, IL-1β, interleukin-27A (IL-17A), and high-mobility group box 1 (HMGB1), followed by a later anti-inflammatory phase marked by IL-10, TGF-β1, and interleukin-27 (IL-27)." (PMID 40868089, 2025). "HMGB1-RAGE signaling links necrosis to macrophage activation and may mediate post-stroke brain injury." (PMID 38740617, 2025). "Therefore, investigation the prognostic value of markers in the NETs/AIM2 inflammasome axis, such as MPO-DNA, PAD4, HMGB1, C1q, AIM2, ASC, Caspase-1, IL-1β, IL-6 and IL-8, in LAA stroke patients is a meaningful endeavor." (PMID 39737165, 2024).
Stroke (continued). "Various triggers, such as febrile seizures, stroke, infection, or trauma, can initiate an inflammatory cascade that releases pro‐inflammatory cytokines, such as IL‐1β and TNF‐α, and danger signals, such as HMGB1." (PMID 38361811, 2024). "(2015) reported that blocking of the HMGB1 and RAGE signaling pathways could eliminate cellular immunosuppression and restore lymphocyte function in the subacute phase after stroke." (PMID 37062906, 2023). "Further studies should identify if the immune markers such as HMGB-1 will remain elevated in poststroke epilepsy as it is elevated after a stroke episode but no alteration in the patients only experiencing epilepsy." (PMID 36338344, 2022). "Through a translational approach studying ischemic stroke patients and employing murine models of ischemic stroke, we report a key role for platelet-derived high-mobility group box 1 (HMGB1) in the formation of NETs in the acute phase of stroke, resulting in exacerbated stroke outcomes." (PMID 35358095, 2022). "After a stroke, RAGE may play a role in a more vigorous inflammatory response that is mediated by HMGB1." (PMID 36421725, 2022). "Patients with stroke had HMGB-1 levels of 7.537 ± 2.074 ng/mL than those without stroke 5.604 ng/mL ± 2.624 (p < 0.0001)." (PMID 36244983, 2022). "Platelets drive HMGB1 release and NET formation, exacerbating stroke outcomes." (PMID 35358095, 2022). "In order to study whether platelet HMGB1 drives NET formation in ischemic stroke, we depleted platelets immediately after stroke onset with an anti-GPIb antibody." (PMID 35358095, 2022). "Finally, we treated WT mice with BoxA, a specific competitive inhibitor of HMGB1, and measured plasma NET levels and stroke outcomes 24 hours after stroke onset." (PMID 35358095, 2022). "The high-mobility group box 1 (HMGB1) protein is released from necrotic and dying neural cells, subsequently activating the NF-κB pathway, which is commonly used as an indicator of inflammation in stroke studies." (PMID 35269418, 2022). "We found, however, that neither mRNA nor protein of Hmgb1 was changed in microglia of stroke mice, as compared to the controls, indicating that stroke selectively induces the expression of Hmgb2." (PMID 34094642, 2021). "Silencing Hmgb1 gene using a small interference RNA that specifically targets Hmgb1 gene (Hmgb1-I), but not Hmgb2 produced no protective effects on stroke damages." (PMID 34094642, 2021). "We found that stroke significantly increased the expression of HMGB1 in the brain homogenates of SHRs compared to shams, but not in normotensive animals." (PMID 33214598, 2020). "The limitations of this study are that we did not measure HMBG1 level nor did we test if the HMGB1 neutralization antibody can alleviate post-stroke memory dysfunction in BF+stroke mice." (PMID 33187248, 2020). "HMGB1 was reported to bind to RAGE or activate the TLR4/MyD88 pathway, both of which promote the reduction of mature monocytes and lymphocytes in the circulation, and lead to subsequent post-stroke immunosuppression." (PMID 31001089, 2019). "We quantified HMGB-1 in serum of the improved and non-improved stroke patient cohort on admission and on day 3 to determine its possible role for maintaining post-stroke immune suppression." (PMID 31118917, 2019). "HMGB1, as an inflammatory cytokine, also can contribute to BBB breakdown, and BBB permeability is significantly reduced by using of anti-HMGB1 monoclonal antibody in experimental stroke models." (PMID 31001089, 2019). "For stroke, there was no reduction in infarct volume or improvement in neurological outcomes, following anti-HMGB1 2G7 treatment, although some alleviated sickness behaviour was documented due to reductions in peripheral immune responses." (PMID 30782181, 2019).
Stroke (continued). "As MRN inhibited Ang II-induced AT1R/RAGE overexpression through the inhibition of HMGB1 secretion and Ang II-mediated downstream signaling, we also speculate that MRN may also be useful for the prevention of stroke as well as cardiac hypertrophy." (PMID 31027372, 2019). "While the investigated immune alterations post-stroke had promptly reversed in the improved cohort, HMGB-1 concentrations were not differentially regulated between the improved and non-improved cohort at the investigated time points." (PMID 31118917, 2019). "Furthermore, HMGB1 and its receptor RAGE have been shown to mediate the ischemic brain damage after stroke." (PMID 30011792, 2018). "Since only a few patients had liver disease (n = 2), renal disease (n = 2), or history of stroke (n = 3), HMGB1 correlations were not studied for those comorbidities." (PMID 30194360, 2018). "Others have shown that in rats whether BBB dysfunction was due to experimental stroke or TBI, a neutralizing monoclonal antibody (mAb) to HMGB1 prevented the BBB dysfunction." (PMID 28890893, 2017). "HMGB1, a ubiquitous non-histone nuclear protein, is a key mediator of the immune mechanism in stroke." (PMID 28152042, 2017). "Others have also shown that BBB dysfunction in rats, whether due to experimental stroke or traumatic brain injury (TBI), can be prevented by a neutralizing antibody to HMGB1." (PMID 27553758, 2016). "In this view, HMGB1 can be considered a hyperacute DAMP, whereas Prx could act as secondary DAMP in the acute phase of stroke." (PMID 27898011, 2016). "We propose that ARBs, which inhibit the HMGB1/RAGE axis, may offer a novel option for prevention and acute treatment of stroke." (PMID 24065095, 2013). "Furthermore, Glycyrrhizin, a HMGB1 inhibitor, significantly attenuated reductions in PBMC numbers 3 d after stroke." (PMID 23555048, 2013). "Additionally, astrocytic HMGB1 (High Mobility Group Box 1), a DAMP molecule, promotes endothelial progenitor cell-mediated vascular remodeling, linking astrocytic stress responses to vascular repair in stroke, a pathology often accompanied by neurodegeneration-associated vascular dysfunction." (PMID 40940752, 2025). "In an in vivo model of cerebral ischemia, injection of HMGB1 siRNA into the ventricle at 5 d after stroke significantly suppressed endothelial progenitor cell (EPC) accumulation and peri-infarct microvessel density and exacerbated the deterioration of neurological prognosis 14 days after stroke." (PMID 38740617, 2025). "By inhibiting HMGB1, GA may attenuate this EPC-driven angiogenesis, suggesting that GA’s therapeutic scope extends beyond inflammation control to modulation of neurovascular repair mechanisms, enriching its neuroprotective profile in stroke management." (PMID 39598404, 2024). "Recently, numerous reports have suggested that HMGB1 as a DAMP is involved in various pathological processes, including stroke, cerebral hemorrhage, inflammatory kidney injury, and heart disease, which suggested that HMGB1 may be one of the key factors that induced neuroinflammation." (PMID 38771510, 2024). "As expected, nNIF treatment did not impact HMGB1 levels after stroke." (PMID 35358095, 2022). "In contrast to post-stroke alterations, where HMGB-1 increase is well-documented, we could not detect any alterations of HMGB-1 after seizures." (PMID 32581999, 2020). "Therefore, therapeutic strategy targeting at HMGB-1/TLR4/NF-κB signaling may be a promising method to limit neuroinflammatory processes and alleviate stroke damage." (PMID 33335763, 2020). "Thus, our present data suggested that EE could promote angiogenesis and functional recovery through increasing astrocytic HMGB1 expression and subsequent inhibition of PSD and PSA during stroke recovery." (PMID 28845299, 2017).
Stroke (continued). "In summary, our data here suggest that post-stroke EE improves stroke outcomes in an apparently pro-angiogenesis manner through astrocytic HMGB1-mediated inhibition of PSD and PSA, and also through astrocytic HMGB1-induced production and secretion of IL-6 from activated astrocytes." (PMID 28845299, 2017). "A recent experimental study showed that genetic or pharmacological blockade of pattern recognition receptor signaling via HMGB1 and receptor for advanced glycation end products (RAGE) abrogated cellular immunosuppression and restored lymphocyte activation in the subacute phase after stroke." (PMID 27923376, 2016). "Therefore, the inhibitory effect of ARBs on the HMGB1/RAGE axis may provide potential therapeutic effects in patients who require prevention and acute treatment of stroke." (PMID 24065095, 2013). "However, the source of HMGB1 as well as the function of HMGB1 in stroke is not well defined." (PMID 35358095, 2022). "Upon activation platelets also express HMGB-1 and expose it on their surface promoting additional NET release by neutrophils, a self-energizing process that even activates the extrinsic coagulation pathway and may be responsible for further thromboinflammation observed after stroke." (PMID 28331857, 2017). "It has further been demonstrated that HMGB1 secreted by reactive astrocytes provides a signal for endothelial progenitor cell (EPC) mediated neurovascular remodeling, and this signaling between glial and vascular compartments may be critically significant for brain repair and stroke recovery." (PMID 29054968, 2017). "Therefore, HMGB1 could be studied in human cerebral artery thrombi by immunochemistry, in order to assess both its presence and whether its expression level varies with stroke etiology or not." (PMID 27152622, 2016). "Extracellular HMGB1 activates multiple membrane receptors, including but not limited to receptor for advanced glycation end products, and TLR4, through which it contributes to the pathogenesis of lung injury, stroke, cancer, and so on." (PMID 31798456, 2019).
diabetes (167 papers, 2011 to 2026). "HMGB1 plays an important role in inflammation-associated diseases, including autoimmune diseases such as systemic lupus erythematosus and diabetes and malignant tumors by promoting the expression of pro-inflammatory cytokines." (PMID 40362678, 2025). "Although some investigations demonstrated that HMGB1 inhibition has encouraging outcomes in the context of diabetes-associated pathologies, to this day, no in vivo study has established a direct causal link between systemic HMGB1 knockdown and hyperglycemia." (PMID 38187339, 2024). "HMGB1 is implicated in the pathogenesis of diabetes, and elevated levels of HMGB1 have been observed in diabetic patients and animal models." (PMID 37065747, 2023). "Autophagy is associated with diabetes-induced organ damage, and the increased expression of HMGB1 leads to excessive autophagy, resulting in a systemic inflammatory response and organ disorders." (PMID 37065747, 2023). "Autophagy is associated with organ damage in diabetes, and increased HMGB1 expression leads to excessive autophagy, which in turn causes systemic inflammation and organ dysfunction." (PMID 37065747, 2023). "Mitochondrial autophagy dysfunction involving HMGB1 is associated with metabolic diseases such as diabetes and fatty liver." (PMID 37065747, 2023). "Inhibiting HMGB1 reduced apoptosis and injury in podocytes and delayed the deterioration of glomerular function caused by diabetes by activating the Akt/mTOR signaling pathway and inhibiting autophagy." (PMID 37065747, 2023). "Activation of HMGB1 and autophagy are associated with the development of various diseases, such as diabetes, tumors, and cardiovascular and cerebrovascular diseases." (PMID 37065747, 2023). "The regulatory role of secreted HMGB1 in diabetes and associated complications, as well as liver disease and cardiovascular diseases, has been shown to be through its binding to different receptors." (PMID 35706377, 2022). "HMGB1 is implicated in the development of diabetes and hyperglycemia, and various associated complications in brain, lung, kidney and bones." (PMID 35706377, 2022). "The results demonstrate that the severity of renal fibrosis is positively associated with the activation of HMGB1/TLR2/4 signaling in diabetes." (PMID 36448056, 2022). "HMGB‐1, a typical damage‐associated molecular pattern protein, exhibited a broad range of biological properties in diabetes and its complications, as discussed in detail in our previous review." (PMID 33724642, 2021). "In chronic inflammatory state associated with diabetes, it was confirmed that high mobility group box 1 (HMGB1) protein, as an activator of TLR and RAGE, promoted the secretion of inflammatory factors." (PMID 33424592, 2020). "Advanced glycation end-product (AGE), receptor for AGE (RAGE), and high mobility group box-1 (HMGB1) are emphasized as the causes of complications in diabetes." (PMID 32821344, 2020). "In line with the observed restoration of normoglycaemia, insulin deficiency and diabetes-induced body weight loss were abolished in anti-HMGB1-treated mice." (PMID 32072192, 2020). "When we used glycyrrhizin in the drinking water of diabetic mice over six months, we found that glycyrrhizin improved permeability, neuronal, and vascular damage associated with diabetes through a decrease in HMGB1." (PMID 31269685, 2019). "We utilized two novel strategies to block HMGB1 signaling via its receptors, and were thereby able to attenuate development of DN in mice with STZ-induced diabetes, indicating a pathogenic role for HMGB1." (PMID 29844451, 2018). "Diabetes up-regulates HMGB1/AGE/RAGE axis gene expression in SMGs that is associated with activation of the nuclear factor kappa B (NF-κB) pathway." (PMID 28099448, 2017). "In the present study, we demonstrated that, similar to diabetes, intravitreal injection of HMGB1 caused a significant upregulation of HMGB1 protein and mRNA and activated cleaved caspase-3 in the retina of normal rats." (PMID 24733965, 2014).